GIPC1 (GIPC PDZ domain containing family member 1)
Description:
May be involved in G protein-linked signaling.
Synonyms: TIP-2; C19orf3; GIPC; RGS19IP1; Hs.6454; SEMCAP; GLUT1CBP; SYNECTIN; NIP; IIP-1; OPDM2; SYNECTIIN
Tractability: Antibody: UniProt places it where antibodies can reach, with medium confidence; the Human Protein Atlas places it where antibodies can reach. PROTAC: ubiquitination databases record sites on it; its protein half-life has been measured.
Gene: Protein-coding gene on chromosome 19 (14,477,759 to 14,496,157, reverse strand). Ensembl gene ENSG00000123159.
Subcellular location: Cytoplasm; Membrane
Subcellular location (Human Protein Atlas): Cell Junctions; Plasma membrane; Nucleoplasm
Pathways (Reactome):
Signal Transduction: FGFR1b ligand binding and activation; FGFR1c ligand binding and activation; TGFBR3 regulates FGF2 signaling; TGFBR3 regulates TGF-beta signaling
Gene Ontology:
Molecular function: cadherin binding; protein binding; signaling receptor binding; actin binding; identical protein binding; myosin binding
Biological process: positive regulation of cytokinesis; positive regulation of melanin biosynthetic process; actin filament organization; chemical synaptic transmission; endothelial cell migration; G protein-coupled receptor signaling pathway; glutamate secretion; negative regulation of proteasomal ubiquitin-dependent protein catabolic process; positive regulation of transforming growth factor beta receptor signaling pathway; protein targeting; regulation of protein stability; regulation of synaptic plasticity; Rho protein signal transduction; presynaptic modulation of chemical synaptic transmission
Cellular component: cell cortex; cytoplasm; cytoplasmic vesicle; extracellular exosome; membrane; cytosol; dendritic shaft; dendritic spine; synaptic vesicle; vesicle membrane; glutamatergic synapse; Schaffer collateral - CA1 synapse
Genetic constraint (gnomAD): Loss-of-function variants: 9 observed, 22.42 expected, observed/expected ratio (o/e) 0.4, 90% interval 0.24 to 0.7. The upper end of that interval is the gene's LOEUF score, 0.7, which puts it in group 2 of 6, group 1 being the genes least tolerant of losing a copy. Missense variants: 397 observed, 430.36 expected, observed/expected ratio (o/e) 0.92, 90% interval 0.85 to 1. Synonymous variants: 203 observed, 185.17 expected, observed/expected ratio (o/e) 1.1, 90% interval 0.98 to 1.23.
Homologues: Orthologues: chimpanzee GIPC1 (99% identical), macaque GIPC1 (99% identical), pig GIPC1 (98% identical), dog GIPC1 (97% identical), mouse Gipc1 (96% identical), rat Gipc1 (96% identical), guinea pig GIPC1 (95% identical), zebrafish gipc1 (82% identical), tropical clawed frog gipc1 (73% identical), Drosophila melanogaster kermit (50% identical), Caenorhabditis elegans gipc-2 (36% identical), Caenorhabditis elegans gipc-1 (35% identical). Paralogues in human: GIPC2 (60% identical), GIPC3 (60% identical).
Diseases named in the same sentence as GIPC1 in open-access papers:
GIPC1 is named in the same sentence as 70 diseases in open-access papers, as found by Europe PMC text mining. Sharing a sentence is not in itself a finding about the gene and the disease. The quoted sentences say what the papers report.
pancreatic cancer (15 papers, 2010 to 2026). "Combination studies were performed to assess the synergistic effects of LGIPCsi and GEM; Results: GIPC1 silencing significantly sensitized pancreatic cancer cells to GEM, resulting in enhanced inhibition of tumor cell proliferation in vitro." (PMID 41155969, 2025). "To overcome these limitations, we developed a liposomal nanoparticle system capable of encapsulating and delivering GIPC1-specific siRNA to pancreatic tumors." (PMID 41155969, 2025). "Before experiments to evaluate the effect of GIPC1 depletion in sensitizing pancreatic cancer cells towards chemotherapeutic drugs, we analyzed the GIPC1 expression levels in AsPC-1, PANC-1, and some PDX cell lines." (PMID 41155969, 2025). "GIPC1 is overexpressed and functional in breast, ovarian, and pancreatic cancer models, promoting growth and migration." (PMID 41374987, 2025). "Our results clearly indicate that depletion of GIPC1 by siRNA also shows a significant reduction in anchorage-dependent and -independent growth in pancreatic cancer." (PMID 31664117, 2019). "Expression levels of NRP1, NRP2 and GIPC1 in nine pancreatic carcinoma cell lines were tested by RT-qPCR and revealed major differences." (PMID 31664117, 2019). "GIPC1 is overexpressed in breast and pancreatic tumors and promotes tumor proliferation, survival, and metastasis; however, its functions have yet to be determined in detail." (PMID 26209534, 2015). "GIPC1 was shown to bind to IGF-1R via its PDZ domain in order to promote pancreatic cancer cell proliferation." (PMID 26209534, 2015). "Suppression of GIPC1 in human pancreatic cancer cells inhibits in vivo tumor growth in immunodeficient mice." (PMID 21209904, 2010). "Most recently, GIPC1 suppression in human pancreatic cancer cells was shown to inhibit in vivo pancreatic tumor growth in immunodeficient mice." (PMID 21209904, 2010). "GIPC1 is highly expressed in a number of human malignancies, including breast, ovarian, gastric, and pancreatic cancers." (PMID 21209904, 2010). "GIPC1 expression could be seen in all the cell lines, corroborating the previous notion that GIPC1 is an essential survival gene in pancreatic cancer." (PMID 41155969, 2025). "Collectively, these findings across four independent pancreatic tumor models validate the robust and reproducible antitumor activity of combined GIPC-1 knockdown and GEM therapy, highlighting the synergistic potential of this strategy to overcome the limited efficacy of monotherapies." (PMID 41155969, 2025). "Next, we intended to see whether GIPC1 depletion in pancreatic cancer cells can increase their sensitivity towards chemotherapeutic drugs such as GEM." (PMID 41155969, 2025). "Upregulation of GIPC1 in pancreatic cancer promotes tumor proliferation and invasion." (PMID 36741321, 2023). "Moreover, a recent report shows GIPC1 is required for in vivo pancreatic tumor growth in immunodeficient mice." (PMID 21209904, 2010). "In pancreatic cancer, the PDZ domain of GIPC1 can stabilize IGF-1R proteins and contribute to cell proliferation." (PMID 38186571, 2023). "After analyzing the PPI network of genes related to GLUT1, we found that GIPC1 54, 55, and SERPINH1 56, 57 were related to the mechanism of tumor metastasis, including in pancreatic tumors." (PMID 35711842, 2022).
breast carcinoma (12 papers, 2008 to 2025). "In the Global Test multivariate analysis of the 689 breast cancer patients, the GIPC1 KD signature is associated with tumor grade (P<0.01), lymph node status (P<0.0001), and ER status (P<0.05)." (PMID 21209904, 2010). "We have determined that GIPC1 is a novel breast cancer-associated immunogenic antigen that is overexpressed in breast cancer." (PMID 18721486, 2008). "To provide a more in depth analysis of these antibodies and to further clarify the association of GIPC1 with different types of breast cancer, we carefully studied 27.F7 and 27.B1 antibodies via immunohistochemical analysis of breast cancer tissue." (PMID 18721484, 2008). "Since we identified GIPC1 as a new tumor-associated antigen that is linked to breast cancer and that stains ovarian cancer cells in vitro, we reasoned that it might be useful as a new marker for these malignancies." (PMID 18721484, 2008). "Therefore, GIPC1 is a novel breast cancer-associated antigen that may play a role in the initiation and/or progression of breast cancer." (PMID 18721486, 2008). "The present pilot study demonstrates that the GIPC1 protein is overexpressed in ovarian and breast cancer, which may provide an important diagnostic and prognostic marker and will constitute the basis for further study of the role that this protein plays in malignant diseases." (PMID 18721484, 2008). "GIPC1 silencing can result in cell cycle arrest in breast cancer cells and regulate cell adhesion and motility through interaction with syndecan-4 (SDC4) via the PI3K signaling pathway." (PMID 38041134, 2023). "Elevated GIPC1 expression levels have been reported in several cancer types, including breast cancer and pancreatic ductal adenocarcinoma, and have been revealed to be associated with a poor prognosis." (PMID 38186571, 2023). "nEASE analysis also suggests that GIPC1 is involved in six major signal transduction networks in breast cancer: integrin-mediated, RHO protein, JAK-STAT, EGF, TGFβ and WNT." (PMID 21209904, 2010). "The chemiluminescent optical fiber immunosensor detected 54% and 77% anti-GIPC-1 AAbs-positive sera within ovarian and breast carcinoma patients, respectively, as compared to ELISA, which only detected 18% and 27%, respectively." (PMID 20145720, 2009). "We identified the protein targets of two of the anti-breast cancer autoantibodies that we isolated, and determined that they target the protein GIPC1." (PMID 18721486, 2008). "An immunohistochemical study of normal ovarian tissue, benign, borderline and malignant ovarian serous tumors, and different types of breast cancer revealed high expression of GIPC1 protein in neoplastic cells." (PMID 18721484, 2008). "Examination of different types of breast cancer demonstrates that the level of GIPC1 expression depends on tumor invasiveness and displays a higher expression than in benign tumors." (PMID 18721484, 2008). "To semi-quantitatively examine gene expression we performed Northern blot analysis to determine if a higher level of GIPC1 specific mRNA was indeed present in the breast cancer cell lines relative to normal cell lines." (PMID 18721486, 2008). "They indicate that breast cancer cells indeed have increased expression of GIPC1 specific RNA relative to that of normal cell lines." (PMID 18721486, 2008). "This indicates that GIPC1-driven PI3K–AKT signaling may be less central in ocular malignancies than in gastric or breast cancer." (PMID 41374987, 2025). "Previously published studies have indicated that antimetastatic effects of Zol correlate with that tumour cell expression of the transcription factor MAF, whereas other studies have shown that high expression of GIPC1 and CAPG is associated with antitumour activity of Zol in breast cancer patients." (PMID 34733240, 2021). "nEASE analysis of GIPC1 KD in MDA-MB231 human breast cancer cells." (PMID 21209904, 2010).
breast carcinoma (continued). "The GIPC1 signature is also strongly associated patient survival within the ERBB2+/ER+ (n = 42, P<0.001), luminal B (n = 146, P<0.05) and basal (n = 92, P<0.01) molecular breast cancer subtypes." (PMID 21209904, 2010). "In particular, our data suggests targeting GIPC1 may be particularly important for estrogen receptor-positive high-grade breast cancers." (PMID 21209904, 2010). "EASE analysis of GIPC1 KD in MDA-MB231 human breast cancer cells." (PMID 21209904, 2010). "We found similar losses of cell viability and increased caspase 3/7 activities after GIPC1 silencing in the MCF-7 and SKBR-3 human breast cancer and SW480 and SW620 human colorectal cancer cell lines (data not shown)." (PMID 21209904, 2010). "Experimental validation of the gene expression profiling results indicates that GIPC1 silencing promotes G2 cell-cycle arrest, apoptosis, and alternations in cell adhesion and motility in MDA-MB231 human breast cancer cells." (PMID 21209904, 2010). "The protein known as GIPC-1, a member of a family of PDZ-domain conserved proteins, is involved in regulation of G-protein signaling and is upregulated in ovarian and breast carcinomas." (PMID 20145720, 2009). "Two of these native fully human monoclonal antibodies (fhMAbs), designated 27.B1 and 27.F7, derived from lymph node B-cells of a breast cancer patient, whose target is the PDZ domain-containing protein known as GIPC1, were chosen for further study." (PMID 18721484, 2008). "GIPC1 has anti-apoptotic effects in human breast and colorectal cancer cells, and the interaction of GIPC1 with MyoGEF, a GEF for RhoA, activates RhoA and promotes breast cancer invasion." (PMID 29659486, 2018). "Moreover, GIPC1 silencing correlates with marked reductions in cell viability and evaluations in caspase 3/7 activities in MCF-7 and SKBR-3 human breast cancer and SW480 and SW620 human colorectal cancer cells." (PMID 21209904, 2010). "By application of an expression cloning technique known as SEREX, we determined that the target antigen for two monoclonal antibodies, 27.B1 and 27.F7, derived from lymph node B-cells of a breast cancer patient, is the PDZ domain-containing protein known as GIPC1." (PMID 18721486, 2008). "In this pilot study we determined that the reactivity of fully human monoclonal antibodies (fhMAbs) 27.B1 and 27.F7, derived from lymph node B-cells of a breast cancer patient and targeting the PDZ domain-containing protein known as GIPC1, are specific to breast and ovarian cancer." (PMID 18721484, 2008). "Human monoclonal antibodies, 27.F7 and 27.B1, to GIPC1 demonstrate specific binding to malignant breast cancer tissue with no reactivity with normal breast tissue." (PMID 18721484, 2008). "The strong staining by the human anti-GIPC1 monoclonal antibodies, 27.B1 and 27.F7, on breast cancer cell lines and absent staining of normal cells suggests that the protein might be up-regulated." (PMID 18721486, 2008). "Therefore, the GIPC1 signature may be capable of distinguishing patient outcome within groups of high-grade breast cancers, particularly those that are ER+, and not simply distinguishing tumor grade (high vs. low) or ER status (positive versus negative)." (PMID 21209904, 2010).
colorectal cancer (5 papers, 2010 to 2026). A primary or metastatic malignant neoplasm that affects the colon or rectum. "Then we engineered GIPC1 overexpression in colorectal cancer cell lines (DLD1, SW480, and HCT116), followed by GIPC1 knockdown in these cell lines." (PMID 41522336, 2026). "To explore the role of GIPC1 in chemoresistance and tumor progression, we measured its expression levels in colorectal cancer cell lines." (PMID 41522336, 2026). "To better understand GIPC1 function, we suppressed its expression in human breast and colorectal cancer cell lines and human mammary epithelial cells (HMECs) and assayed both gene expression and cellular phenotype." (PMID 21209904, 2010). "In this study, we used both computational and experimental approaches to examine GIPC1 in human breast and colorectal cancer cells, and in patients with breast and ovarian cancer." (PMID 21209904, 2010). "To investigate the role that GIPC1 plays in cancer, we used RNAi to suppress GIPC1 expression in both breast and colorectal cancer cells and human mammary epithelial cells (HMECs)." (PMID 21209904, 2010). "We found that GIPC1 is required for breast and colorectal cancer cell survival, and it plays an essential role in oncogenic transformation of human mammary epithelial cells." (PMID 21209904, 2010). "Our analysis indicates that GIPC1 is required for breast and colorectal cancer cell survival and plays an essential role in oncogenic transformation." (PMID 21209904, 2010). "GIPC1 has dual functions in the progression and metastasis of MACC1-driven primary colorectal cancer." (PMID 41522336, 2026). "We employed GIPC1/MACC1-manipulated cell lines for in vitro and in vivo analyses, and we probed the GIPC1/MACC1 impact using human primary colorectal cancer (CRC) tissue." (PMID 38144523, 2023). "IHC analysis of tissue microarrays from CRC patients and collected colorectal cancer (CRC) samples and adjacent normal tissues, showed decreased GIPC1 expression in CRC tissues compared to non-malignant tissues." (PMID 41522336, 2026).
oculopharyngodistal myopathy (5 papers, 2022 to 2025). Oculopharyngodistal myopathy (OPDM) is a rare, adult-onset hereditary muscle disease. "These include NOTCH2NLC repeat expansion in NIID and intronic CCG repeat expansions in NUTM2B-AS1, LRP12 and GIPC1 causing oculopharyngeal myopathy with leukoencephalopathy, oculopharyngodistal myopathy (OPDM) types 1 and 2, respectively." (PMID 39349043, 2025). "Oculopharyngodistal myopathy (OPDM) is a group of disorders caused by mutations in several genes such as LRP12, GIPC1, NOTCH2NLC and RILPL1." (PMID 39501809, 2024). "The expansion of several other CGG repeats located in 5’ UTRs have been implicated in oculopharyngodistal myopathy (OPDM): NOTCH2NLC, GIPC1, LRP12, RILPL1, and ABCD3." (PMID 39868092, 2025).
ovarian carcinoma (4 papers, 2008 to 2025). A malignant neoplasm originating from the surface ovarian epithelium. "Analysis of the ovarian cancer dataset indicates that the GIPC1 signature is significantly associated with all clinical variables assessed; including patient survival and tumor stage, grade, and type." (PMID 21209904, 2010). "One common feature of the correlations we found between the GIPC1 signature and clinical parameters in breast and ovarian cancer was an association with high-grade tumors that are characterized by excessive DNA damage and poor patient prognosis." (PMID 21209904, 2010). "To further clarify the association of GIPC1 with breast and ovarian cancer we carefully studied 27.F7 and 27.B1 using immunocytochemical and immunohistochemical techniques." (PMID 18721484, 2008). "Therefore, we extended our studies of GIPC1 in breast and ovarian cancer to determine the utility of this cancer-associated antigen as a marker for malignancy." (PMID 18721484, 2008). "In the ovarian cancer dataset, the GIPC1 signature is statistically correlated with all clinical variables assessed: overall survival and tumor grade, type, and stage." (PMID 21209904, 2010). "We compared this GIPC1 signature to publicly available breast and ovarian cancer gene expression datasets for which well-annotated phenotype and outcome data were available." (PMID 21209904, 2010). "The chemiluminescent optical fiber immunosensor detected 77% and 54% anti-GIPC-1 AAbs positive sera within breast and ovarian carcinoma patients, respectively, as compared to ELISA, which only detected 27% and 18%, respectively." (PMID 21113302, 2010). "Clinical relevance of the set of top 411 differentially expressed GIPC1 KD probesets (absolute fold change > 2) to human breast and ovarian cancers." (PMID 21209904, 2010). "This GIPC1 signature statistically correlates with a number of breast and ovarian cancer phenotypes and clinical outcomes, including patient survival." (PMID 21209904, 2010). "In glioblastoma and ovarian cancer, GIPC1 promotes angiogenesis by amplifying VEGF signaling." (PMID 41155969, 2025). "Additionally, a GIPC1 knock-down gene signature was used to interrogate publically available breast and ovarian cancer microarray datasets." (PMID 21209904, 2010). "In particular, a study of GIPC1 protein expression in malignant cells of ovarian tumors might provide new avenues for the diagnosis, prognosis and treatment of ovarian cancer, and might constitute the basis for further study of the role that this protein might play in malignant disease." (PMID 18721484, 2008). "The protein known as GIPC-1, a member of a family of PDZ-domain conserved proteins, is involved in regulation of G-protein signaling and is upregulated in breast and ovarian carcinomas." (PMID 21113302, 2010).
bone metastasis (3 papers, 2018 to 2023). Transfer of a neoplasm from its primary site to bones. "Patients with high expression of CAPG and GIPC1 treated with zoledronic acid showed a tenfold reduction in the risk of bone metastasis compared to the control group (P = 0.008)." (PMID 38041134, 2023). "CAPG showed a weak association, and GIPC1 expressed a stronger relation with bone metastasis." (PMID 30155403, 2018). "Using primary tumor tissue from patients in the AZURE study, we showed that a novel composite biomarker comprising the proteins CAPG and GIPC1 was prognostic for developing bone metastasis (HR = 4.5, 95% CI = 2.1 to 9.8, P < .001) and predicted response to zoledronate (P = .008)." (PMID 29425304, 2018).